MEX3A (mex-3 RNA binding family member A)
Diseases named in the same sentence as MEX3A in open-access papers (continued):
Sharing a sentence is not in itself a finding about the gene and the disease.
glioma (continued). "The immunohistochemical staining of MEX3A in glioma and normal tissues revealed the upregulation of MEX3A and further indicated the relationship between high MEX3A expression and higher malignancy as well as poorer prognosis of glioma." (PMID 33414423, 2021). "The Kaplan–Meier survival analysis, showing the poorer prognosis of patients with higher MEX3A expression, further suggested the involvement of MEX3A in glioma development." (PMID 33414423, 2021). "First of all, in order to explore the role of MEX3A in glioma, the quantification of its expression in glioma and normal tissues was measured by IHC analysis." (PMID 33414423, 2021). "In terms of the results of the observation and measurement of tumor-bearing mice models, the promotor role of MEX3A in the development and progression of glioma was further clarified in vivo." (PMID 33414423, 2021). "In this study, in order to identify a novel therapeutic target for glioma treatment, we explored the functions and mechanism of MEX3A in regulating glioma." (PMID 33414423, 2021). "Based on the construction of MEX3A- knockdown cell models or xenografts, in vitro and in vivo loss-of-function studies were carried out to clarify the exact roles of MEX3A in the regulation of phenotypes of glioma." (PMID 33414423, 2021). "All the in vivo experiments give results that agree with the in vitro studies, showing the inhibition of glioma by MEX3A knockdown." (PMID 33414423, 2021). "Considering the high aggressiveness of glioma, the regulation of MEX3A on cell migration was also assessed by Transwell assay, showing the observably suppressed migration ability by MEX3A knockdown." (PMID 33414423, 2021). "Finally, we divided all glioma patients into high and low MEX3A mRNA expression groups using the median expression level as a cut-off." (PMID 40958871, 2025). "From the transcriptome data analysis results in the public database, it was found that CDK4, PBK, ANGPTL2, TMEM100, and MEX3A were significantly up-regulated in the glioma samples compared with the normal samples, whereas NEGR1 and SLC2A3 were down-regulated in the glioma samples at the mRNA level." (PMID 36358948, 2022). "In addition, the knockdown of ANGPTL2 and MEX3A reduces the proliferative and invasive abilities of glioma cells." (PMID 36358948, 2022). "For MEX3A, it may promote glioma development by regulating cell proliferation, cell apoptosis, cell cycle and cell migration, and MEX3A has been identified as a potential tumor promoter in glioma development and therapeutic target in glioma treatment." (PMID 36101384, 2022). "Finally, the endogenous expression of MEX3A in glioma cell lines, including U87, U251, U373, and SHG-44, was detected and proved." (PMID 33414423, 2021). "In addition, they reported that MEX3A exerted its ubiquitination role to induce glioma tumorigenesis." (PMID 34189143, 2021). "In addition, patients with relatively higher MEX3A expression were often diagnosed as advanced with a shorter survival period, which implied the potential role of MEX3A in the development of glioma." (PMID 33414423, 2021). "In vivo experiments also suggested the inhibition of glioma growth by MEX3A knockdown." (PMID 33414423, 2021). "More importantly, we further illustrated that knockdown of CCL2 could alleviate or reverse the promotion effects of MEX3A overexpression on glioma, indicating its potential role as the downstream of MEX3A." (PMID 33414423, 2021). "Moreover, the correlation analysis between MEX3A expression and clinical parameters of glioma patients revealed a positive correlation between higher MEX3A levels and higher tumor malignancy." (PMID 33414423, 2021). "In other words, these results clarified that MEX3A could promote the development of glioma, in which CCL2 may be involved." (PMID 33414423, 2021). "All these results implied that the role of MEX3A in glioma deserves further investigation." (PMID 33414423, 2021).
glioma (continued). "Our results demonstrated that MEX3A may promote the development of glioma through regulating CCL2 expression." (PMID 33414423, 2021). "Conversely, cell apoptosis was significantly promoted in glioma cells with MEX3A knockdown." (PMID 33414423, 2021). "In vitro loss-of-function and gain-of-function experiments comprehensively demonstrated that MEX3A may promote glioma development through regulating cell proliferation, cell apoptosis, cell cycle, and cell migration." (PMID 33414423, 2021). "Thus, modulating MEX3A levels could not only impact tumor proliferation but also reshape the immune landscape of gliomas." (PMID 40958871, 2025). "Moreover, MEX3A has been suggested to promote tumor development in glioma by targeting CCL2." (PMID 35490173, 2022). "Furthermore, the effects of MEX3A on glioma cell migration could be partially explained by the downregulated expression of EMT-related proteins, including N-cadherin, Snail, and Vimentin." (PMID 33414423, 2021). "Moreover, our mechanistic study identifies CCL2 as a potential downstream target of MEX3A, which possesses similar regulatory effects on glioma development with MEX3A and could attenuate the promotion of glioma induced by MEX3A overexpression." (PMID 33414423, 2021). "The upregulated or downregulated MEX3A expression in glioma regulated the development and progression of glioma through targeting CCL2, which provided a reference that MEX3A may be served as a prognostic marker and a novel therapeutic target in glioma treatment." (PMID 33414423, 2021). "Further studies are needed for the better understanding the role of MEX3A and RIG-1 circuitry in gliomas pathogenesis, including the heterogeneity of the stem cells in gliomas (GSCs)." (PMID 40958871, 2025). "Subsequently, following the construction of a molecular interaction network revealing the potential linkage between MEX3A and CCL2, we deduced that CCL2 may be a downstream target of MEX3A in the regulation of glioma." (PMID 33414423, 2021). "A series of cell phenotypes was subsequently evaluated using the glioma cells with or without MEX3A knockdown." (PMID 33414423, 2021). "Moreover, the gain-of-function study of MEX3A and phenotype “rescue” experiments of the MEX3A/CCL2 axis were used for verifying the regulatory effects of MEX3A/CCL2 in glioma." (PMID 33414423, 2021). "Herein, we verified that, similar with MEX3A, CCL2 was also upregulated in glioma tissues relative to normal tissues." (PMID 33414423, 2021).
ovarian carcinoma (6 papers, 2021 to 2023). A malignant neoplasm originating from the surface ovarian epithelium. "It was shown that MEX3A is overexpressed in ovarian cancer tissues and associated with increased proliferation and invasion of ovarian cancer cells." (PMID 36833284, 2023). "Through our research, we found that MEX3A was overexpressed in ovarian cancer and associated with poor prognosis in ovarian cancer patients." (PMID 35715407, 2022). "TIMELESS knockdown impaired phenotypic changes in ovarian cancer cells caused by MEX3A overexpression." (PMID 35715407, 2022). "We used bioinformatics analysis to screen and identify the key RBPs in ovarian cancer, from which we found that Mex-3 RNA Binding Family Member A (MEX3A) was intimately associated with the clinical prognosis of ovarian cancer." (PMID 35715407, 2022). "Our analysis of MEX3A expression in clinical samples and open access online database supported that MEX3A was significantly upregulated in ovarian cancer, and high levels of MEX3A in ovarian cancer patients were associated with shorter survival time." (PMID 35715407, 2022). "Thus, MEX3A has the potential to be a new diagnostic biomarker and therapeutic target for ovarian cancer patients." (PMID 35715407, 2022). "For example, the inhibition of MEX3A expression results in excessive ROS production and lipid peroxidation, thereby enhancing ferroptosis in ovarian cancer." (PMID 37433225, 2023). "We also detected MEX3A protein expression in ten cases of ovarian cancer and 6 cases of normal fallopian tube fresh tissue by western blotting." (PMID 35715407, 2022). "We identified TIMELESS as an important target involved in MEX3A in mediating the growth and metastasis of ovarian cancer cells." (PMID 35715407, 2022). "In this study, we revealed that MEX3A was overexpressed in ovarian cancer tissues and correlated with worse prognosis of ovarian cancer patients." (PMID 35715407, 2022). "Through the analysis of TCGA and CCLE databases, the results showed that there was a linear positive relationship between MEX3A amplification and its mRNA expression in both ovarian cancer tissues and cell lines." (PMID 35715407, 2022). "To confirm the function of TIMELESS in MEX3A-mediated proliferation, migration, and invasion of ovarian cancer cells, we transiently transfected TIMELESS siRNA into HEY cells overexpressing MEX3A." (PMID 35715407, 2022). "In contrast, the upregulation of MEX3A promoted the malignant biological behavior of ovarian cancer cells." (PMID 35715407, 2022). "Above all, we identified that TIMELESS contributed to MEX3A’s carcinogenic function in ovarian cancer." (PMID 35715407, 2022). "In conclusion, we first confirmed the expression, biological roles and regulatory mechanism of MEX3A in ovarian cancer." (PMID 35715407, 2022). "MEX3A facilitated the proliferation and invasion of ovarian cancer cells by regulating alternative splicing of TIMELESS through the NMD pathway." (PMID 35715407, 2022). "In this case, we observed that MEX3A was highly overexpressed in fresh-frozen ovarian cancer tissues." (PMID 35715407, 2022). "MEX3A knockdown suppressed the development and invasion of ovarian cancer cells, while MEX3A overexpression promoted the proliferation and invasion of ovarian cancer cells." (PMID 35715407, 2022). "The results showed that the expression of MEX3A protein in ovarian cancer tissue was significantly higher than that in normal fallopian tube tissues." (PMID 35715407, 2022). "In ovarian cancer, MEX3A has been found to promote malignant progression by guiding intron retention in TIMELESS." (PMID 36614043, 2022).
ovarian carcinoma (continued). "Kaplan–Meier analysis revealed that patients with higher expression of MEX3A (62.16%) correlated positively with poor prognosis for patients with ovarian cancer." (PMID 35715407, 2022). "Taken together, the MEX3A/TIMELESS axis promoted the malignant biological behavior of ovarian cancer cells." (PMID 35715407, 2022). "In this study, we analyzed RNA-seq data after MEX3A knockdown in ovarian cancer cells and identified the critical downstream target TIMELESS involved in the alternative splicing regulation of MEX3A." (PMID 35715407, 2022). "To verify the function of MEX3A in ovarian cancer cells, we devised two kinds of small interfering RNAs (siRNAs) to downregulate MEX3A expression and constructed MEX3A overexpression cell lines by lentivirus transfection in ovarian cancer cells." (PMID 35715407, 2022). "The results showed that MEX3A expression was mainly focused in the nucleus, and MEX3A expression was higher in ovarian cancer than that in normal fallopian tube tissues." (PMID 35715407, 2022). "The results of this paper demonstrated that the MEX3A/TIMELESS signaling pathway was a key regulator of ovarian cancer, and MEX3A was a novel possible treatment target for ovarian cancer patients." (PMID 35715407, 2022). "The results showed that MEX3A expression was significantly increased in ovarian cancer tissues compared to normal fallopian tubes." (PMID 35715407, 2022). "MEX3A copy number amplification occurred in 10% of ovarian cancer samples in TCGA cohort, and MEX3A mRNA expression increased in patients with amplification." (PMID 35715407, 2022). "The results showed that MEX3A was overexpressed in ovarian cancer tissues and involved in the poor prognosis of ovarian cancer patients." (PMID 35715407, 2022). "TIMELESS was reported to be aberrantly expressed and intimately associated with the development and progression of human cancers, and therefore we selected TIMELESS as the key target of MEX3A in ovarian cancer." (PMID 35715407, 2022). "High expression group of MEX3A accounted for 62.16% of all the ovarian cancer samples, and high level of MEX3A correlated with ascites volume and poor overall survival." (PMID 35715407, 2022). "Immunohistochemistry staining assay was performed to further evaluate MEX3A expression in ovarian cancer and normal fallopian tube tissues based the Tissue Microarray (TMA) of high-grade serous ovarian cancer from our tissue bank." (PMID 35715407, 2022). "Therefore, the MEX3A/TIMELESS oncogenic signaling pathway is a key regulator of ovarian cancer, which is suppressed by AS-NMD in normal cells." (PMID 36833284, 2023). "MEX3A accelerated the malignant biological behavior of ovarian cancer." (PMID 35715407, 2022). "A series of experiments confirmed that MEX3A gene knockdown could inhibit the proliferation and invasion of ovarian cancer cells." (PMID 35715407, 2022). "Moreover, the results of subcutaneous implanted tumors in female nude mice suggested that MEX3A knockdown remarkably inhibited the tumor growth of ovarian cancer cells and led to a decrease in tumor weight and volume." (PMID 35715407, 2022). "MEX3A knockdown was found to decrease the invasion and migration abilities of ovarian cancer cells." (PMID 35715407, 2022). "Moreover, we used a Transwell assay to determine the roles of MEX3A in the metastasis of ovarian cancer cells." (PMID 35715407, 2022). "In our research, we analyzed the expression and biological functions of MEX3A in ovarian cancer." (PMID 35715407, 2022). "MEX3A promoted the malignant biological progression of ovarian cancer both in vitro and in vivo." (PMID 35715407, 2022). "The study showed that MEX3A promotes the metastasis capacity of ovarian cancer cells." (PMID 35715407, 2022). "Additionally, we found that TIMELESS overexpression with MEX3A knockdown partially restored the proliferation ability of ovarian cancer cells." (PMID 35715407, 2022).
ovarian carcinoma (continued). "Consistent with the results of colony formation assays in vivo, xenograft experiments showed TIMELESS knockdown could partially reverse the effect of MEX3A overexpression on the growth of ovarian cancer cells in vivo." (PMID 35715407, 2022). "MEX3A might regulate immune infiltration in the microenvironment of ovarian cancer cells and is a potential therapeutic target." (PMID 35715407, 2022). "Furthermore, qRT-PCR and western blotting were used to evaluate TIMELESS expression after MEX3A knockdown in ovarian cancer cells, and we found that TIMELESS mRNA and protein expression was obviously decreased after MEX3A inhibition." (PMID 35715407, 2022). "The role of MEX3A in alternative splicing regulation was unclear in ovarian cancer until now." (PMID 35715407, 2022). "Therefore, TIMELESS is the main target that mediates the role of MEX3A in the growth and metastasis of ovarian cancer cells." (PMID 35715407, 2022). "The genes coexpressed with MEX3A were subjected to functional and pathway enrichment analyses, and the results indicated that they were mainly involved in the immune response processes during tumorigenesis and progression of ovarian cancer." (PMID 34189143, 2021). "Furthermore, correlation analysis between 182 DEGs and MEX3A was applied using TCGA ovarian cancer data to obtain 7 DEGs (CSNKE1, OBSL1, DNASE1, ZNF711, TIMELESS, SAMD11, and BCL9) that were positively associated with MEX3A expression (Spearman’s correlation≥0.3)." (PMID 35715407, 2022). "To study the mechanism by which MEX3A promotes the malignant biological progression of ovarian cancer, we performed RNA-seq after MEX3A knockdown in A2780 cells to analyze the changes in differentially expressed genes (DEGs) between the MEX3A-NC group and the si-MEX3A#1 group." (PMID 35715407, 2022). "Therefore, our research showed that MEX3A served as an oncogene in ovarian cancer." (PMID 35715407, 2022). "However, the correlations of MEX3A with prognosis and its molecular mechanism in ovarian cancer (OC) remain unclear." (PMID 34189143, 2021). "To reveal the mechanism by which MEX3A regulates TIMELESS expression in ovarian cancer, we observed intron 23 retention of TIMELESS mRNA based on Sashimi plot analysis according to the RNA-seq results after MEX3A knockdown." (PMID 35715407, 2022). "Further studies will be needed to evaluate the clinical value of the MEX3A target for ovarian cancer treatment by constructing PDX mouse models and organoid models of ovarian cancer patients." (PMID 35715407, 2022). "Correlation analysis between MEX3A and TIMELESS verified that TIMELESS expression was positively correlated with MEX3A expression in ovarian cancer tissues." (PMID 35715407, 2022). "The development of novel small-molecule inhibitors of MEX3A or the targeted inhibition of MEX3A expression using methods such as MEX3A blocking peptide, ASO, or AAV would suppress the growth and metastasis of ovarian cancer cells and improve the clinical prognosis of patients." (PMID 35715407, 2022). "However, the relationship between MEX3A and ovarian cancer is not yet known." (PMID 35715407, 2022).
bladder urothelial carcinoma (5 papers, 2017 to 2021). "Therefore, this study aimed to determine the relationship between mex3a and bladder urothelial carcinoma." (PMID 28903380, 2017). "Moreover, the expression levels of mex3a in the papillary type of bladder urothelial carcinoma were higher than those of the non-papillary type." (PMID 28903380, 2017). "Mex3a expression was not a poor prognostic factor of bladder urothelial carcinoma." (PMID 28903380, 2017).
Wilms tumor (5 papers, 2017 to 2021). An embryonal neoplasm characterized by the presence of epithelial, mesenchymal, and blastema components. "MEX3A has been identified to be associated with diseases, especially cancer, such as Wilms tumors, gastric carcinomas, colorectal carcinomas." (PMID 32140076, 2020). "For example, MEX3A overexpression is associated with the recurrence of Wilms tumors." (PMID 32140076, 2020). "Furthermore, the overexpression of mex3a was associated with the relapse of Wilms tumors." (PMID 28903380, 2017).
lung adenocarcinoma (4 papers, 2020 to 2025). A carcinoma that arises from the lung and is characterized by the presence of malignant glandular epithelial cells. "But little is known about the expression and function of Mex3a in lung adenocarcinoma." (PMID 32792503, 2020). "In lung adenocarcinoma (LUAD), it modulates the PI3K/AKT pathway via the circGRAMD1B/miR-4428/SOX4/MEX3A axis, enhancing migration, invasion, and EMT." (PMID 40282289, 2025).
lung carcinoma (4 papers, 2021 to 2025). "The cross-correlation of EIF4E3/MEX3A has been defined in breast and lung cancers." (PMID 39940786, 2025).